ERICH6B (glutamate rich 6B)
Synonyms: FAM194B; FLJ32682
Tractability: PROTAC: ubiquitination databases record sites on it.
Gene: Protein-coding gene on chromosome 13 (45,534,522 to 45,615,739, reverse strand). Ensembl gene ENSG00000165837.
Genetic constraint (gnomAD): Loss-of-function variants: 68 observed, 81.37 expected, observed/expected ratio (o/e) 0.84, 90% interval 0.69 to 1.02. The upper end of that interval is the gene's LOEUF score, 1.02, which puts it in group 4 of 6, group 1 being the genes least tolerant of losing a copy. Missense variants: 745 observed, 825.21 expected, observed/expected ratio (o/e) 0.9, 90% interval 0.85 to 0.96. Synonymous variants: 280 observed, 302.84 expected, observed/expected ratio (o/e) 0.92, 90% interval 0.84 to 1.02.
Homologues: Orthologues: chimpanzee ERICH6B (94% identical), macaque ERICH6B (90% identical), dog ERICH6B (44% identical), mouse Erich6b (34% identical), tropical clawed frog siah3 (14% identical). Paralogues in human: ERICH6 (16% identical), FAM194C (9% identical).
Diseases named in the same sentence as ERICH6B in open-access papers:
ERICH6B is named in the same sentence as 2 diseases in open-access papers, as found by Europe PMC text mining. Sharing a sentence is not in itself a finding about the gene and the disease.
ERICH6B shares sentences with these, for which no sentence is quoted: cancer (1 paper); tumour (1).